RUNX2 (RUNX family transcription factor 2)
Diseases named in the same sentence as RUNX2 in open-access papers (continued):
Sharing a sentence is not in itself a finding about the gene and the disease.
thyroid tumor (5 papers, 2013 to 2022). A benign or malignant neoplasm affecting the thyroid gland. "RUNX2 also plays a central role in mediating the pro-migratory and pro-invasive function of thyroid tumor cells, by activating the expression of MMP2, MMP13, MMP14 and OPN." (PMID 26204939, 2015). "Further, we showed that the transcription factor RUNX2, also a target of Id1, is a crucial mediator of the Id1 pro-invasive function in thyroid tumor cells." (PMID 24069422, 2013). "We recently showed that RUNX2 is a crucial mediator of the Id1 aggressive phenotype in thyroid tumor cells." (PMID 24069422, 2013). "This suggests that other pathways cooperate with the TGF-β signals in controlling RUNX2 expression in thyroid tumor cells." (PMID 24069422, 2013). "We showed that TGF-β signaling pathway is constitutively activated in thyroid tumor cells and suggested that RUNX2 and CDH6 is part of this pathway." (PMID 24069422, 2013). "However, Runx2 expression was upregulated in thyroid tumor tissues (TP) compared to both normal thyroid tissues (GTEX) and tumor adjacent thyroid tissues (NT)." (PMID 36497320, 2022). "Overall, these data demonstrate that CDH6 expression is controlled by RUNX2 in thyroid tumor cells." (PMID 24069422, 2013). "In this work, we show for the first time that CDH6 is a novel TGF-β target gene in thyroid cells, and we demonstrate that its expression is controlled by RUNX2, which we have recently shown to be an important mediator of aggressive phenotype in thyroid tumor cells." (PMID 24069422, 2013). "Based on these observations we can hypothesize a model in which RUNX2 is the major mediator of TGF-β signaling in controlling the expression of CDH6 in thyroid tumor cells." (PMID 24069422, 2013). "Moreover, RUNX2 regulates cellular invasion in thyroid tumour cells." (PMID 31043660, 2019). "However, siRNA mediated RUNX2 ablation does not completely abolish the TGF-β effect on CDH6 expression suggesting that other TGF-β–dependent factors beside RUNX2 may be involved in controlling this gene in thyroid tumor cells." (PMID 24069422, 2013).
tooth agenesis (5 papers, 2010 to 2023). A tooth disease characterized by failure to develop one or more missing teeth. "Our findings suggest that the method developed in this study shows potential for future clinical applications aimed at treating patients with congenital tooth agenesis resulting from Runx2 mutation." (PMID 34211084, 2021). "In our study, some borderline association was observed for the studied genetic polymorphisms in RUNX2, suggesting that future studies should investigate the association of variations in this gene with isolated tooth agenesis in a larger population." (PMID 34539446, 2021). "There are many lines of evidence that suggest the duplication of RUNX2 may be causative in these two individuals including the converse dental phenotype of hypodontia to that seen in individuals with heterozygous RUNX2 inactivation." (PMID 20683987, 2010). "Runx2 is involved in the whole process of tooth development, and Runx2 knockout mice are a representative congenital tooth agenesis model." (PMID 36467684, 2022). "The findings suggested that Runx2−/− mice may be suitable as murine models of congenital tooth agenesis." (PMID 34211084, 2021).
acute lymphoblastic leukemia (4 papers, 2015 to 2025). Leukemia with an acute onset, characterized by the presence of lymphoblasts in the bone marrow and the peripheral blood. "High RUNX2 expression correlates with bad prognosis in BCR-ABL1-positive acute lymphoblastic leukemia (ALL) patients." (PMID 26404249, 2015).
aortic valve disease (4 papers, 2020 to 2023). "Existing studies have demonstrated that, TUG1, high expression in calcified aortic valve disease, can play a role of sponge to adsorb miR-204-5p, up-regulate Runx2 expression, and promote osteoblastic differentiation in CAVD." (PMID 35358011, 2022). "Moreover, activated BMP signalling has been shown to increase expression of cartilage and bone-type collagens, and increased expression of the osteogenic marker Runt-related transcription factor 2 (Runx2)/core-binding factor subunit alpha-1 (CBF α-1) is observed in adult aortic valve disease." (PMID 32867198, 2020).
Arthritis (4 papers, 2019 to 2024). Inflammation of a joint. "The changes in SFPQ and RUNX2 expression in patients with OA indicate the potential importance of SFPQ and RUNX2 in the progression of arthritis." (PMID 36915153, 2023). "The results from in vivo experiments indicated that EZP combined with MTX reduced arthritis severity, alleviated ankle bone damage, increased BALP and decreased TRACP serum levels, and regulated the mRNA expression of Wnt1, LRP5, β-catenin, Runx2, BALP, and BGP in the ankles." (PMID 32218732, 2020).
bone metastasis (4 papers, 2015 to 2022). Transfer of a neoplasm from its primary site to bones. "Several bone metastasis-associated genes induced by TGF-β were revealed to be an indirect effect, such as RANKL, RUNX2, CXCR-4, CTGF and IL-11." (PMID 26697526, 2015).
head and neck cancer (4 papers, 2017 to 2024). A primary or metastatic malignant neoplasm affecting the head and neck. "PTHLH expression is controlled by RUNX2 and is correlated with head and neck cancer growth." (PMID 28120940, 2017).
invasive breast carcinoma (4 papers, 2014 to 2021). A carcinoma that infiltrates the breast parenchyma. "For RUNX2, the alteration with the highest frequency was amplification, with a percentage of 2.74% in breast invasive carcinoma NOS and 1.62% in breast invasive ductal carcinoma." (PMID 34485309, 2021). "Rictor expression is upregulated by Runt-related transcription factor (Runx2) in invasive breast cancer cells." (PMID 31595162, 2019). "We find that Runx2 is required to maintain pAkt (Serine 473) levels in a subset of invasive breast cancer cells." (PMID 24479521, 2014). "The subtypes with the highest frequency of all alternate types were breast invasive lobular carcinoma, breast invasive carcinoma NOS, and breast invasive ductal carcinoma for RUNX1, RUNX2, and RUNX3, respectively." (PMID 34485309, 2021). "The invasive breast cancer-derived MDA-MB-231 cells express increased levels of Runx2 compared to non-tumorigenic MCF-10A cells." (PMID 24479521, 2014).
metastatic prostate carcinoma (4 papers, 2012 to 2021). A carcinoma that arises from the prostate gland and has spread to other anatomic sites. "We have presented evidence that integration of two different signaling pathways (CD44 and αvβ3) facilitate osteoclastogenesis and bone loss via a RUNX2/Smad5/RANKL axis in metastatic prostate cancer cells." (PMID 22966907, 2012). "There were several key proteins found in in bone and bone metastatic prostate cancer, including RUNX2." (PMID 33308223, 2020).
oral cancer (4 papers, 2021 to 2024). "miR-23a-3p can inhibit the PI3K/Akt signaling pathway by targeting Runx2 and inhibit the malignant evolution of oral cancer." (PMID 35342401, 2022). "Immunohistochemistry analysis also showed a positive correlation between the expression of MRE11 and RUNX2 in oral cancer tissues." (PMID 33927349, 2021). "RUNX2 expression was found to be increased by MRE11 in oral cancer." (PMID 37108164, 2023). "In oral cancer (both HSC-3 and Ca9-22 cells), RUNX2 expression was positively regulated by MRE11, the nuclease component of the RAD50/MRE11/NBS1 DNA repair complex." (PMID 37108164, 2023). "A positive correlation between the expression of RUNX2 and CXCR4, as determined by immunohistochemistry analysis, was observed in oral cancer tissues." (PMID 33927349, 2021).
pituitary tumor (4 papers, 2016 to 2020). A benign or malignant neoplasm affecting the pituitary gland. "First, that transcription factors Runx1 and Runx2 regulate Galectin-3 expression in human pituitary tumors." (PMID 30930748, 2019).
pulmonary arterial hypertension (4 papers, 2014 to 2024). Pulmonary arterial hypertension (PAH) is a group of diseases characterized by mean pulmonary artery pressure >20 mmHg and elevated pulmonary arterial resistance leading to right heart failure. "It has been documented that miR-204 may act through RUNX2 to inhibit osteogenesis in mesenchymal progenitor cells, and expression of miR-204 has been widely recognized has a key factor in vascular remodeling in pulmonary arterial hypertension." (PMID 25232725, 2014).
vitamin D deficiency (4 papers, 2017 to 2024). A nutritional condition produced by a deficiency of VITAMIN D in the diet, insufficient production of vitamin D in the skin, inadequate absorption of vitamin D from the diet, or abnormal conversion of vitamin D to its bioactive metabolites. "The effect of early life vitamin D deficiency on the DNA methylation of Runx2, Osterix, VDR, and RXRA, genes known to play essential roles in bone formation, was assessed." (PMID 35619053, 2022). "Early life vitamin D deficiency is associated with altered methylation of osterix and Runx2 in these bones." (PMID 35619053, 2022). "Future studies will investigate the role of FGF23 in stimulating expression of Runx2 and Runx2 target genes and enhancing transcriptional activity of Runx2 leading to increased biogenesis of tumor supportive EMVs that drive the vicious cycle and contribute to vitamin D deficiency." (PMID 28300755, 2017).
anemia (3 papers, 2019 to 2024). A reduction in the number of red blood cells, the amount of hemoglobin, and/or the volume of packed red blood cells. "MYC+RUNX2-DKO leukemic cells were transplantable in secondary recipient mice with the same CD11b−CD11cmid/+B220+Bst2+ immunophenotype, and recipient mice died earlier at 2 weeks post-transplantation (the median survival, 23 days) due to severe anemia and thrombocytopenia." (PMID 30971697, 2019).
cartilage disease (3 papers, 2021 to 2025). Softening and degeneration of the CARTILAGE. "Molecular modifications that affect the activity of MMP-13 or RUNX2 could change the abnormal function not only of cartilage but also meniscus, facing OA as a whole-joint disease and not as a cartilage disease." (PMID 40724902, 2025).
co-infection (3 papers, 2017 to 2021). "Data analysis showed that co-infection with anti-miR-340-5p and shRUNX2 reduced the level of RUNX2, contrary to that down-regulation of miR-340-5p enhanced RUNX2 expression." (PMID 33818278, 2021). "When the expression of osteogenic regulators and markers were assessed, we found that BMP9-induced expression of Runx2 in iMEFs was dramatically reduced by AdsimH19 co-infection." (PMID 28881833, 2017). "However, co-infection of AdR-simRmst effectively blunted BMP9-induced expression of both Runx2 and Osx." (PMID 31825894, 2019).
endothelial dysfunction (3 papers, 2019 to 2020). In vascular diseases, endothelial dysfunction is a systemic pathological state of the endothelium (the inner lining of blood vessels) and can be broadly defined as an imbalance between vasodilating and vasoconstricting substances produced by (or acting on) the endothelium.
fibrosis (3 papers, 2023 to 2024). the formation of excess fibrous connective tissue in an organ or tissue in a reparative or reactive process. "Additionally, substantially elevated RUNX2 expression was observed in the liver tissues of patients with cirrhosis and fibrosis model mice." (PMID 37957540, 2024). "In addition, it is known that Runx2 contributes to the development of vascular fibrosis in diabetes mellitus in mice in vivo." (PMID 39595568, 2024). "The upregulation of RUNX2 was verified in the cirrhosis, NAFLD, NASH and HBV‐related fibrosis datasets." (PMID 37957540, 2024).
glioblastoma (3 papers, 2011 to 2025). The most malignant astrocytic tumor (WHO grade IV). "ECOP is co-amplified with EGFR in glioblastoma as well as other cancers, RUNX2 is expressed in glioblastoma cells, and PCDH11X is associated with late-onset Alzheimer's disease." (PMID 21510904, 2011).
hematoma (3 papers, 2022 to 2025). A hematoma is a collection of blood from a vascular structure into an extravascular space. "In line with this, the expression of osteogenic differentiation markers RUNX2, ALP, BMP4, and Noggin as well as the chondrogenic differentiation marker SOX9 were all significantly lower in smokers’ hematomas (comp." (PMID 35621464, 2022). "Treatment with MBE could not rescue the ALP activity of the smoker in vitro facture hematomas and showed a slight trend in inducing RUNX2 and SOX9 expression." (PMID 37569229, 2023).
kidney cancer (3 papers, 2022 to 2024). Primary or metastatic malignant neoplasm involving the kidney. "Prior studies have also observed that high RUNX2 expression in kidney cancer is associated with a mesenchymal phenotype which promotes tumour cell migration, invasion and proliferation in vitro, and with higher tumour grade in vivo." (PMID 39282259, 2024). "RUNX1 and RUNX2 genes might be also involved in kidney cancer." (PMID 34973136, 2023).
lung diseases (3 papers, 2022 to 2025). "The transcriptomic analysis previously identified RUNX2 as a deregulated gene in the PAH dataset, and RUNX2 also appears in the LC-PAH CCP, suggesting that it is also a critical TF for other lung diseases." (PMID 36551878, 2022).
nephrolithiasis (3 papers, 2017 to 2022). The presence of a calculus in the pelvis of the kidney; this is most often composed of mineral salts and proteins. "Genes encoding for Runx1, Runx2, KRT 18, KRT 8, VIM, Fn-1, Col1a1 and Col1a2 were up regulated during hyperoxaluric conditions and further increased after crystal deposition or nephrolithiasis." (PMID 29091707, 2017).
neuroblastoma (3 papers, 2013 to 2023). Neuroblastoma (NB) is the most common solid, extracranial childhood tumor.
renal carcinoma (3 papers, 2013 to 2025). A carcinoma arising from the epithelium of the renal parenchyma or the renal pelvis. "Based on these findings, our study confirms that EA inhibits MMP1 expression by downregulating RUNX2, thereby suppressing the migration and invasion abilities of renal cancer cells." (PMID 40386045, 2025). "Overall, our study demonstrated that the inhibitory effect of EA on renal cancer cell migration and invasion is mediated through the inhibition of the RUNX2/MMP1 axis." (PMID 40386045, 2025).
T-cell acute lymphoblastic leukemia (3 papers, 2022 to 2025). Acute lymphoblastic leukemia of T-cell origin. "It was observed that RUNX2 drives the generation of mature human NK cells and regulates leukemic cell metabolism and chemotaxis in patients with T-cell ALL." (PMID 40881686, 2025). "Additionally, enhanced glycolysis is observed in T-cell acute lymphoblastic leukemia (T-ALL) and is induced by oncogenes, including runt-related transcription factor 2 (RUNX2) neurogenic and locus notch homolog protein (NOTCH)." (PMID 36483029, 2022).
thymic lymphomas (3 papers, 2019 to 2023). "Briefly, Runx2 neutralizes the pro-apoptotic effect of Myc overexpression and confers a potent survival advantage to thymic lymphomas in Runx2/Myc-ERTM mice (CD2-Runx2 mice crossed with CD2-Myc-ERTM mice)." (PMID 36831211, 2023).
thyroid (3 papers, 2019 to 2024). "Recently, we described a relevant role for activator protein-1 (AP1) in driving thyroid tumorigenesis by controlling the expression of the pro-oncogenic factor Runt-related transcription factor 2 (RUNX2)." (PMID 31200515, 2019).
viral infections (3 papers, 2019 to 2022). "In contrast, RUNX2 contributes to clear viral infections through promoting IL-1 production in plasmacytoid dendritic cells." (PMID 35665333, 2022). "Hdac6 is reported to interact with Runx2 as well as being involved in multiple cellular processes, including organization of the immune synapse, cell migration, protein degradation, and viral infections." (PMID 31815961, 2019).
acromegaly (2 papers, 2019 to 2021). Acromegaly is an acquired disorder related to excessive production of growth hormone (GH) and characterized by progressive somatic disfigurement (mainly involving the face and extremities) and systemic manifestations. "Notably, overexpression of RUNX2 can compromise bone quality, as we have demonstrated in acromegaly patients." (PMID 34638677, 2021).
acute kidney injury (2 papers, 2018 to 2021). Sudden and sustained deterioration of the kidney function characterized by decreased glomerular filtration rate, increased serum creatinine or oliguria. "There was a significant downregulation of runt-related transcription factor 2 (RUNX2) expression in Group 1 (normal control rats without renal failure)." (PMID 34830159, 2021).
acute leukemia (2 papers, 2019 to 2025). A clonal (malignant) hematopoietic disorder with an acute onset, affecting the bone marrow and the peripheral blood. "Blastic plasmacytoid dendritic cell neoplasm (BPDCN) is a rare and an aggressive subtype of acute leukemia with strongly RUNX2 expression, and RUNX2 is also required for the tumor cell differentiation and migration." (PMID 31311566, 2019).
adenoma (2 papers, 2023 to 2026). A neoplasm arising from the epithelium. "RUNX2 overexpression promoted proliferation, invasion, migration, and adenoma-to-adenocarcinoma transition-related markers in HCT116 and HCT15 cells, while its knockdown reversed these effects." (PMID 42056097, 2026). "The RUNX2-specific inhibitor CADD522 suppressed RUNX2 expression in vitro and inhibited the adenoma-to-adenocarcinoma transition in the AOM/DSS model." (PMID 42056097, 2026). "Conversely, TNFRSF1A inhibitor Atrosab downregulated RUNX2 expression and partially reversed RUNX2 overexpression-induced adenoma-to-adenocarcinoma transition." (PMID 42056097, 2026). "Gal-3 levels further increase in the progression from PRL and ACTH-secreting adenomas to carcinomas; gene methylation plays a role in Gal-3 expression, and RUNX1 and RUNX2 transcription factors seem to target its gene directly, enhancing its expression." (PMID 37958702, 2023). "In summary, CD8+ Tex cells may activate RUNX2 in malignant EPCs through TNF-α binding to TNFRSF1A, promoting the adenoma-to-carcinoma transition and contributing to poor prognosis." (PMID 42056097, 2026).
aortic stenosis (2 papers, 2020 to 2023). Aortic valve stenosis is a aortic valve disease caused by the incomplete opening of the aortic valve. "Within this pathway, the key enzyme of COX-2 was considered as an important drive for aortic stenosis by increasing valvular calcification and enhancing osteogenic genes including OPN and Runx2." (PMID 32423380, 2020). "A further step in the development of aortic stenosis is the mineralization of the valve due to the transition of VIC into osteoblast-like VIC characterized by a variety of osteoblastic markers, such as osteopontin, bone morphogenetic protein 2 (BMP2) and Runt-related transcription factor 2 (RUNX2)." (PMID 36982932, 2023).